INS (insulin)
Diseases named in the same sentence as INS in open-access papers (continued):
Sharing a sentence is not in itself a finding about the gene and the disease.
Obesity (continued). "Induction of glycerol kinase and activation of the “futile” cycle could reduce the efflux of free fatty acids, whose levels in serum correlate with obesity-related insulin insensitivity." (PMID 25884368, 2015). "Our findings thus may suggest that obesity and plasma insulin levels have substantial influence on the activation of dACC, supporting food intake via basic metabolic mechanisms and potentially independent from subjective motivation." (PMID 26099208, 2015). "We studied whether perivascular adipose tissue (PVAT) controls insulin-induced vasodilation in human muscle, and whether altered properties of PVAT relate to reduced insulin-induced vasodilation in obesity." (PMID 26003324, 2015). "Insulin signals satiety after a meal; however, the rising incidence of obesity and chronic insulin elevation suggests that insulin may also signal reward." (PMID 26503322, 2015). "Because MnTBAP is a metalloporphyrin molecule, we hypothesized that its anti-obesity and insulin sensitizing actions may be regulated by heme oxygenase-1 (HO-1), as had been shown for cobalt porphyrins." (PMID 26397111, 2015). "Resistin has been reported to be related to obesity and insulin in patients with T2D." (PMID 25945322, 2015). "Since hyper-insulinemia is generally observed in genetically obese mice, the elevation of insulin is most likely the consequence of the obesity rather than the loss of Brs3 function." (PMID 26020940, 2015). "With HFSD, the onset of obesity was gradual in our experimental model and was set up by week 12 in females with a 40% increase in body weight, enhanced levels of fasting glycaemia and plasma insulin levels." (PMID 25909471, 2015). "Impaired insulin signaling pathway may therefore, as with leptin, contribute to the development of neuropsychiatric symptoms in the context of obesity by interacting with brain cytokines." (PMID 26190966, 2015). "A subset of obese individuals are often described as metabolically healthy obese and are characterized by high insulin sensitivity which may protect them to some extent against obesity-related metabolic complications." (PMID 26640243, 2015). "Obesity and insulin may contribute to the initiation and progression of a variety of tumors and are linked to low response to antitumor drugs." (PMID 26084465, 2015). "Given that leptin levels are increased in obesity and that, due to selective leptin resistance, its proinflammatory and insulin desensitizing effects are maintained, body weight reduction is important in diabetic patients as a strategy to preserve insulin efficacy." (PMID 26578976, 2015). "The growth period of adolescence and young adulthood may be a critical time for shaping future adiposity and our study demonstrates that, in mice, repression of insulin hypersecretion during this life stage can provide long-term protection against obesity." (PMID 26155745, 2015). "There is a lot of evidences that attenuation of 5-HT2CR signaling leads to hyperphagia, disturbed energy expenditure, obesity, reduced insulin sensitivity, and the hypothalamic melanocortin system closely linked to 5-HT2CR is involved in these metabolic and behavioral changes." (PMID 28031898, 2015). "Therefore, we herein investigated the effects of L-Cit on insulin signaling improvements in rat hepatoma H4IIE cells, which have the ability to produce glucose and have been used to develop an obesity-related insulin-resistant model." (PMID 26084330, 2015). "Future research will need to help determine whether obesity or reduced insulin sensitivity is the principal driver for earlier pubertal onset." (PMID 26061526, 2015). "Thus, the compensation for insulin resistance in these cells in obesity is crucial to avoid eventual progression to hyperglycaemia and type 2 diabetes." (PMID 26108563, 2015).
Obesity (continued). "As the relationship between obesity and mortality changes with increasing age, the identified gene expression signatures, in particular those related to insulin signaling and oxidative stress defense, might also be affected in a younger cohort." (PMID 26470795, 2015). "Why insulin-induced microvascular recruitment is blunted in obesity is unclear." (PMID 26003324, 2015). "Besides, we observed that among the DE genes there was an overrepresentation of the obesity and the insulin resistance pathways." (PMID 24926690, 2014). "Along these lines, the GG genotype was associated with higher HOMA-IR and insulin, but not with obesity, in a cohort of obese and normal weight Spanish subjects." (PMID 24562334, 2014). "In obesity beta-cell mass increases by 30–40% whereas insulin secretory output augments by 100%." (PMID 24734255, 2014). "What are the roles of obesity and the increase of insulin in the progression of bone maturation?" (PMID 24994575, 2014). "Obesity-related indexes, such as the weight, blood fat, and insulin, significantly increased." (PMID 24818015, 2014). "Regulation of IDE activity by insulin is of interesting as there is hyperinsulinemia in obesity." (PMID 24740421, 2014). "By regulating food intake and obesity, leptin indirectly impacts insulin sensitivity, but emerging evidence suggests that leptin may also directly regulate insulin signaling." (PMID 25674466, 2014). "Lack of physical activity coupled with obesity and associated changes in circulating levels of insulin, IGF, mTOR and associated kinases have been strongly implicated in this regard." (PMID 25553771, 2014). "However, the spectrum of diabetic conditions differs in characteristics of insulin production and obesity profile as well as cytokine and lipid levels." (PMID 25137300, 2014). "Based on this evidence it is also tempting to speculate that p110γ inhibition may have a more generic role in modulation of cancer cell metabolism beyond the context of obesity and insulin resistant conditions." (PMID 25360116, 2014). "While rexinoids have demonstrated insulin sensitizing, glucose lowering and anti-obesity effects in animal models of disease they have been associated with undesirable effects as hypertriglyceridemia and suppression of the thyroid hormone axis both in animals and in humans." (PMID 25143786, 2014). "First, in a study using C3aR knockout mice, C3aR was proposed to be a determinant of metabolic dysfunction, where C3aRKO mice were transiently protected from the metabolic effects of high fat diet/obesity-induced insulin resistance and adipose tissue inflammation." (PMID 24743347, 2014). "In individuals without overt T2DM, obesity is an insulin-resistant state associated with hyperinsulinemia and a modest expansion of β-cell mass, estimated to correspond to an increase of 10%-30% for each 10 kg of excess body weight." (PMID 24524730, 2014). "High fructose water uptake for 8 weeks induced (F and F2 groups) metabolic changes characterized by metabolic syndrome as indicated by a noticeable increase in the obesity index, serum insulin, lipid profile, and the upward shifting of the glucose tolerance curve." (PMID 25045706, 2014). "We previously showed that individuals carrying heterozygous variants in the 1–631 region of SH2B1 were hyperphagic, with a reduced final height, elevated plasma insulin levels that are disproportionate to the degree of obesity, and surprisingly, maladaptive behavior." (PMID 24971614, 2014). "These include obesity dependent mechanisms as well as alternate pathways such as the impact of fructose on unregulated hepatic lipogenesis and fatty acid oxidation which subsequently leads to inactivation of the insulin signaling pathway." (PMID 24555673, 2014).
Obesity (continued). "Conditioned medium from RAW cells over-expressing Fas (in response to LPS stimulation) decreased insulin-stimulated glucose uptake into L6 myotubes, potentially recapitulating the link between obesity-induced monocyte Fas over-expression and muscular insulin resistance." (PMID 24203314, 2014). "In drug discovery and testing, the db/db mouse is the most popular animal model used by pharmaceutical companies to test glucose lowering agents, insulin sensitizers, insulin secretagogues, and anti-obesity agents, although ob/ob mice, Zucker fatty rats and ZDF rats are also widely used." (PMID 24809394, 2014). "Further, while there is a positive association of testosterone and free testosterone with obesity, serum androstenedione has not been shown to increase with obesity or insulin levels in women with and without hirsutism." (PMID 25310562, 2014). "Multivariable logistic regression models found that patients were significantly more likely to be in the top 10% or the top 20% of the total cost distribution if they had a CCI score ≥ 2; had received a diagnosis of renal impairment, obesity, or hypertension; or were treated with insulin." (PMID 24576356, 2014). "A novel finding was that fasting and post-OGTT plasma α-KG concentrations were major discriminating variables when comparing the pre-intervention phase (insulin-resistant, sedentary obesity) and post-intervention phase (improved insulin sensitivity and physical fitness)." (PMID 24416208, 2014). "In the studies concerning the development of HT in diabetic patients, clinical factors, such as poor metabolic control, high daily insulin dose and overweight/obesity, are usually, but not always, implicated as causative." (PMID 24562335, 2014). "The authors of this study found that PPAR-γ expression was required for action of the thiazolidinedione drug pioglitazone to restore insulin sensitivity in obesity, as pioglitazone enhanced the accumulation of VAT Treg and improved insulin sensitivity in obese mice." (PMID 25157251, 2014). "Although OSA is associated with manifestations of the metabolic syndrome, recent studies in healthy human volunteers revealed that increasing HI is associated with worsening insulin IR independent of obesity." (PMID 25937854, 2014). "In conclusion, DUSP2 plays no role in regulating obesity-associated inflammation and only a minor role in controlling insulin sensitivity following HFD in female, but not male, mice." (PMID 25375135, 2014). "Following the same lines of evidence, in a study of 284 volunteers with various levels of waist to hip ratio, the differences in blood pressure by LEPR variants remained significant after adjusting for the influence of obesity and body fat distribution, as well as insulin and leptin." (PMID 24772364, 2014). "Thus, overnutrition induces hypothalamic ER stress, leading to insulin and leptin resistance and obesity." (PMID 25541737, 2014). "DD intervention in mice resulted in obesity and elevated insulin and glucose level in the blood." (PMID 24886035, 2014). "Studies reporting roles for the MAPK dual specificity phosphatases DUSP1 and DUSP9 during inflammation, obesity and insulin sensitivity, prompted us to investigate what function DUSP2 might play in these processes." (PMID 25375135, 2014). "Insulin, amylin, and preptin are co-secreted from pancreatic beta cells in response to increased glucose levels after feeding, and are also found in high circulating levels in obesity." (PMID 24847313, 2014). "However, it was recently reported that in male C57BL/6J mice taurine supplementation in the drinking water enhanced hypothalamic insulin action which in turn decreased energy intake and prevented high-fat diet-induced obesity." (PMID 24658997, 2014).
Obesity (continued). "The stimulatory effect of insulin on sympathetic drive, vascular smooth muscle growth and sodium and water retention and its inhibitory effect on prostacyclin synthesis have been suggested to be involved in the pathogenesis of obesity-related hypertension." (PMID 24559270, 2014). "However, this assumption was not confirmed, which allows us to suggest that the Amazonas tucumã has a different fatty acid composition that can lead to the development of obesity, resistance to insulin, and dyslipidemia." (PMID 25165578, 2014). "In addition, circulating levels of TG and cholesteryl esters (CE) are also elevated in obesity and have been shown to affect fasting glucose and insulin sensitivity." (PMID 25520669, 2014). "Likewise, decreased carnitine in muscle, liver and kidney has been found to be a common trait of the insulin resistant state, including diet-induced obesity, genetic diabetes and aging." (PMID 25424121, 2014). "As high-fat, obesity-promoting diets clearly inhibit insulin sensitivity as well as lifespan, it is logical to suppose that the enhanced insulin sensitivity induced by CR may be responsible for its effects on healthspan and lifespan." (PMID 25674466, 2014). "This leads to a major restoration of energy balance by increasing insulin, increasing motivation for palatable food, and mobilizing stored energy toward central stores that leads to obesity." (PMID 25225489, 2014). "In humans, data on the role of this adipokine in insulin sensitivity and obesity are controversial." (PMID 24741591, 2014). "Since all animals showed an increase in body mass, a tendency to develop obesity and probably a metabolic alteration (i.e., resistance to insulin) could be established." (PMID 25165578, 2014). "Other contributors to obesity-related cancer progression are insulin/IGF-1 pathways and hormones." (PMID 25505738, 2014). "Rationale: Insulin (INS) resistance associated with hyperestrogenemias occurs in gestational diabetes mellitus, polycystic ovary syndrome, ovarian hyperstimulation syndrome, estrogen therapies, metabolic syndrome, and obesity." (PMID 25101056, 2014). "Obesity-associated metabolic mediators and hormones such as insulin, estrogen, and progesterone were not significantly regulated by obesity." (PMID 25354395, 2014). "While this discovery is encouraging as it mimics the heterogeneous human response to obesity, it requires investigators who may use this model in the future to carefully identify insulin-resistant animals prior to randomization and treatment." (PMID 25215301, 2014). "The present study demonstrated that the obesity-related conditions of elevated glucose, insulin and IGF-1 levels may increase cell viability and in selected cases, resistance to chemotherapy and accumulation of the global transcription factor, HIF-1." (PMID 24396438, 2014). "Meanwhile, MSTN knock out enhances systemic insulin sensitivity and prevents obesity." (PMID 25859286, 2014). "Differences in body weight and the degree of obesity strongly impact insulin action." (PMID 25244011, 2014). "Using a diet-induced obesity mouse model, we observed enhanced insulin sensitivity in obese mice administered IFNT compared to control mice, which was accompanied by a significant decrease in secretion of proinflammatory cytokines and elevated anti-inflammatory macrophages (M2) in adipose tissue." (PMID 24905566, 2014). "Moreover, depletion of CD8+ T cells in diet-induced obesity resulted in decreased accumulation of macrophages into obese VAT as well as improved insulin sensitivity." (PMID 25157251, 2014). "Insulin actions are highly regulated by many factors, including a large number of endocrine, inflammatory, neural, and cell-intrinsic agents, which have been shown to be dysregulated in obesity." (PMID 24466104, 2014). "We demonstrated that daily insulin requirements were Some clinicians believe that obesity may occur due to more flexible and frequent feeding with carb counting method." (PMID 24932599, 2014).
Obesity (continued). "There is controversy about the insulin clearance in obesity." (PMID 24740421, 2014). "Since FAAH is regulated by both insulin and leptin, we hypothesise that factors such as insulin and leptin resistance in obesity oppose any further increases in FAAH activity and that MGL must be under other regulating factors." (PMID 24593280, 2014). "Plasma omentin levels and gene expression in adipose tissue decrease with obesity and correlate positively with plasma adiponectin and high-density lipoprotein levels and negatively with waist circumference, BMI, and insulin levels, all of which are markers of MetS." (PMID 24741591, 2014). "Obesity is the primary phenotypic manifestation observed in the various leptin- and leptin receptor-deficient rodents, but they also display some T2DM-like characteristics such as hyperglycemia, glucose intolerance, and elevated plasma insulin." (PMID 24809394, 2014). "Interestingly, obesity also reduced infarct size in an model of insulin-insensitive rats, probably through increased AKT-eNOS phosphorylation." (PMID 25432364, 2014). "With the alarming rise of obesity and obesity-related diseases, understanding the endocrine functions of adipose tissue and adipocyte-secreted adipokines in regulating systemic metabolism and insulin sensitivity has become critical." (PMID 24552349, 2014). "It has also been proposed that obesity may affect the secretion of certain hormones such as insulin and sex steroids, which may act on the thyroid to stimulate cell proliferation and suppress apoptosis." (PMID 25421041, 2014). "Insulin (INS) resistance associated with hyperestrogenemias occurs in gestational diabetes mellitus (GDM), polycystic ovary syndrome (PCOS), ovarian hyperstimulation syndrome (OHSS), estrogen therapies, metabolic syndrome, and obesity." (PMID 25101056, 2014). "Furthermore, increased water intakecould decreased the insulin resistance in animal models of obesity." (PMID 25361538, 2014). "The most commonly postulated being the “insulin–cancer hypothesis”, suggesting that obesity results in chronic hyperinsulinaemia." (PMID 25255691, 2014). "However, the subpopulation of Cd11c macrophages, reported to be recruited to adipose tissue in obesity and to have deleterious effects on insulin sensitivity, appeared to be increased in the adipose tissue of MK2−/−." (PMID 25233471, 2014). "Furthermore, administration of vaspin suppresses leptin, TNFα, and resistin, reduces food intake, and improves glucose control and insulin sensitivity in obesity." (PMID 24899788, 2014). "In some studies, it has been mentioned that factors like obesity, hypertension, dyslipidemia, poor glycemic control, insulin, and so forth may be contributory factors for the presence of GERD symptom in type II DM patients." (PMID 25530757, 2014). "Therefore, our interest was to evaluate alterations in biochemical and inflammatory parameters, as well as insulin and glucose homeostasis during the obesity-aging process." (PMID 24979131, 2014). "FOXO transcription factors appear to orchestrate many of the beneficial responses to caloric restriction and may therefore represent an interesting target for improving metabolism in the presence of obesity and increased insulin levels." (PMID 25136826, 2014). "There is suggestive evidence that this variant contributes to the obesity of the NZO strain, since the Lepr locus appeared to enhance the effect of the QTL Nob1 (later identified as Tbc1d1) on body weight and serum insulin in female (SJLxNZO)NZO backcross mice." (PMID 24752583, 2014). "Prospective studies indicate that, at 6 years of age, as at birth, the greatest increase in weight-to-height ratio (relative obesity) was seen in children who experienced the greatest exposures to insulin in the uterus (as judged by amniotic fluid insulin concentration)." (PMID 25093191, 2014).